ERBB4 (erb-b2 receptor tyrosine kinase 4)
Diseases named in the same sentence as ERBB4 in open-access papers (continued):
Sharing a sentence is not in itself a finding about the gene and the disease.
tumor (continued). "In summary, the involvement of NRG1 in promoting ERBB3-mediated signaling and the formation of oncogenic heterodimers with ERBB1, ERBB2, and ERBB4 highlights the significance of NRG1 fusions in driving abnormal cell proliferation and tumor progression." (PMID 38957319, 2024). "Pharmacologic inhibition of ERBB4 partly controls ALCL cell growth and disease progression in an ERBB4-positive patient-derived tumor graft model." (PMID 37810974, 2023). "In a cohort of 80 UM patients, ErbB2 (HER2) was expressed in all tumor samples and its expression was significantly higher than EGFR and ErbB4 (p<0.001)." (PMID 38021158, 2023). "In this regard, interaction involving the WW domains of YAP with other DNA-binding transcription factors like p73, ERBB4, EGR-1, RUNXs have also been reported which results in context-dependent oncogenic or tumor-suppressive outcomes." (PMID 35526072, 2022). "Previously, it has been shown that Wwox exerts its tumor suppressor function via interacting with p73, AP2-γ,C-jun, ErbB-4 and finally Dvl proteins 12, 34-38." (PMID 32368285, 2020). "The dramatically increased BTC‐mediated tumor burden was EGFR‐dependent, but also ERBB4 and ERBB2 were involved in PDAC development or progression, as depletion of EGFR, ERBB2, or ERBB4 significantly improved the survival rate of BTC‐mediated PDAC." (PMID 32335999, 2020). "Detailed analyses of structural alterations and CNVs of this tumor revealed a gain at the NRG3 gene, a ligand for ERBB4 and ERBB3 receptors, that was previously shown to play a role in ERBB pathway activation." (PMID 30499260, 2019). "We have also found that erbB4 promotes the phosphorylation of PLC-γ, a protein that promotes the pathogenesis of many tumor types." (PMID 31291965, 2019). "Previously, miR-520a has been proved to modulate the expression of ErbB4 and suppresses the proliferation and invasion of ESCC cells in vitro, indicating its role as a tumor suppressor." (PMID 30956903, 2019). "Ereg was first identified from the cultured medium of fibroblast-derived tumor cell lines and directly bound to activate EGFR, and ERBB4." (PMID 31761787, 2019). "Upon scoring the number of erbB4 positive tumor cells in each MPNST, we found that in most (16/25) tumors, the majority [> 75% (4+) or 50–75% (3+)] of the tumor cells were erbB4 immunoreactive." (PMID 31291965, 2019). "Given that ERBB4 is one of many upstream regulators of AKT signaling, the cholesterol enriching tumor phenotype should be common in many ERBB4 expressing cancers." (PMID 31847457, 2019). "Overall, ERBB4 expression and activation in the GBM tumor or the surrounding vessels contributes significantly to GBM microvessel growth and stability, making ERBB4 a possible anti-angiogenic target." (PMID 30044378, 2018). "The ErbB family of RTKs, which consist of Epidermal growth factor receptor (EGFR) (ErbB1 or HER1), ErbB2 (HER2 or Neu), ErbB3 (HER3), and ErbB4 (HER4), have been shown to promote tumor progression in various cancer types." (PMID 27902463, 2017). "Analysis of tumor tissue lysates by phospho-RTK array showed a prominent tyrosine phosphorylation of EGFR, ERBB4, INSR and IGF1R in control which was remarkably decreased in tumor from treated mice." (PMID 27374103, 2016). "We performed immunostaining of EGFR, ASAP1, ERBB2, ERBB4 and β-catenin in HBL tumor tissue from an expanded cohort of children treated with liver transplantation (n = 19) or with surgical resection (n = 40) and biopsy (n = 1)." (PMID 27910913, 2016). "Our findings demonstrated that ErbB4 was up-regulated in ESCC, and expression of ErbB4 was correlated with tumor differentiation and lymph node metastasis." (PMID 24438167, 2014).
tumor (continued). "In our analysis eight new candidate tumor suppressor genes were identified, OXSR1 (3p22.2), BSG(19p13.3), NT5E(6q14.3), PLEKHG7(12q22), CMTM8(3p22.3), NETO2(16q12.1), ODZ3(4q35.1) and ERBB4(2q34)." (PMID 25551557, 2014). "However, we note that disrupting the BH3 domain or the amino-terminal LXXLL motif of ErbB4 abrogates the tumor suppressor activity of the ErbB4 Q646C mutant, suggesting that ErbB4 targeting to the nucleus and mitochondria is important for the tumor suppressor activity of the ErbB4 Q646C mutant." (PMID 24791013, 2013). "PI3K, which interacts directly with and is regulated by ERBB4, is required for Rac1 activation, and PI3K activation supports metastasis in many tumour types." (PMID 23681745, 2013). "A similar phenomenon has been described for other RTKs such as EGFR, ErbB2, ErbB3, ErbB4 and VEGFR2 where truncated versions had functional implications for the growth of the tumor cells." (PMID 24205204, 2013). "We have excluded the possibility that ADAM17 contributes to MC38CEA tumor progression via shedding of the ligands for EGFR and ErbB4." (PMID 23251384, 2012). "Further, we determined binding of CL4 on stable tumor derived cell lines that differently express EGFR family members (EGFR, ErbB2, ErbB3, or ErbB4)." (PMID 21915281, 2011). "c-ErbB2 tumours demonstrate overexpression of EGFR, ErbB2, ErbB3 and ErbB4, and activation/phosphorylation of both ErbB2 and ErbB3, underscoring the importance of the entire EGFR family in ErbB2-induced tumourigenesis." (PMID 18700973, 2008). "In contrast, ErbB-3 mRNA was much higher in the primary tumours (and matched normal kidney) than in RCC cell lines, while ErbB-4 message was markedly reduced in tumours compared to normal." (PMID 15956968, 2005). "Of note, p63 promotes mammary gland maturation via transactivation of NRG1 in the luminal layer by p63 in the basal layer, resulting in ERBB4/STAT5 signalling driving luminal differentiation, a process which remains to be validated in vivo in the tumour context." (PMID 38238426, 2024). "Furthermore, miR-193a-5p suppresses LC metastasis by targeting ERBB4/PIK3R3/mTOR/S6K2, and this tumor suppressor was upregulated in males but downregulated in females." (PMID 38245882, 2024). "Surprisingly, ERBB3‐ and ERBB4‐KO cells show a completely different behavior, no changes in proliferation and tumor growth, and even accelerated migration." (PMID 37341059, 2023). "Among them, ERBB4 and NPM1 are presumably involved in cSCC tumorigenesis; in addition, GNAQ, GNAS, JAK2, NRAS, IDH2, and CTNNB1 may be related to tumor metastasis." (PMID 36780540, 2023). "Eight cases with tumor depth >10 mm showed mutations in CSF1R, ERBB4, FLT3, KDR, and NPM1, regardless of lymph node metastasis." (PMID 36780540, 2023). "We analyzed tumor samples submitted to Caris Life Sciences (n=64,354), as well as the TCGA (n=10,967), MSK IMPACT (n=10,945) and AACR GENIE (n=96,324) databases for evidence of EGFR, ERBB2 and ERBB4 gene fusions." (PMID 37168365, 2023). "In total, recurrent (>3) MEI were observed in 329 protein-coding genes of which 28 genes are annotated in the Cancer Gene Consensus with either oncogenic (ALK1, ERBB4, TSHR, PREX2, CTNNA2, CTNND2) or tumour suppression roles (EBF1, LRP1B, PTPRD, GPC5, ROBO2, PTPRT)." (PMID 35301290, 2022). "In this study, mutations in the genes ARID1A, APC, ERBB4, NCOR1, PDGFRA, ATM, and CDKN2A were either non-recurrent or of very low frequency, while none of the 14 sequenced EP tumours harboured mutations in the genes HRAS, EGFR, or RB1." (PMID 34045664, 2022).
tumor (continued). "The present study also suggests AP-1/GGA2 can support the expression of other RTKs, MET and ErbB4, which might have a significant impact on cancer growth in HCC, since MET is known to be overexpressed in this type of tumor." (PMID 34799560, 2021). "In addition to KRAS, miR-193a-3p acts on multiple signaling pathways and plays a tumor-suppressive role by regulating the expression of interleukin 17 receptor D (IL17RD) and erb-b2 receptor tyrosine kinase 4 (ERBB4) in CRC." (PMID 35111681, 2021). "Intratumoral variability was evident, with both erbB4-positive and –negative tumor cells present in the same neoplasm." (PMID 31291965, 2019). "Although we have previously shown that broad-spectrum erbB inhibitors inhibit Ras activation, Erbb4 ablation did not affect Ras activation, suggesting that erbB4 drives neoplasia via non-Ras dependent pathways." (PMID 31291965, 2019). "In our study, genes, such as GATA3, ERBB4, RET, NAT1, and TFF3, typically more expressed in ER positive tumor samples, were also more expressed in stromal cells from ER positive as compared with ER negative tumors (defined by immunohistochemistry of malignant cells)." (PMID 31817155, 2019). "EGFR and PTEN were used as positive and negative controls respectively, and ERBB4 copy number is similar to the known tumor suppressor PTEN." (PMID 29342193, 2018). "If ERBB4 is behaving as a tumor suppressor, only the receptor or the ligand—but not both—needs to be missing in order for there to be loss of tumor suppressor activity i.e. cancer progression." (PMID 29342193, 2018). "A deeper investigation of copy number data in tumor tissue samples from GBM patients in TCGA and the general, healthy population in DECIPHER disproved our initial hypothesis that ERBB4 may be acting as a tumor suppressor in GBM." (PMID 29342193, 2018). "Furthermore, ERBB4E317K xenografts had a significantly higher tumor MVD than U87MG or U87ERBB4 xenografts (p = 0.03), indicating that increased ERBB4 activation contributes to vascularization." (PMID 30044378, 2018). "Our findings suggest that miR-302b may be a novel CRI regulating miRNA that inhibits CRI critical pathway and downstream cytokines expression through targeting ERBB4, IRF2 and CXCR4, resulting in decrease of tumor growth." (PMID 28467773, 2017). "We also identified three tumors with targetable RTK lesions (PDGFRA, ERBB2, ERBB4) that were exclusive to the recurrent tumor (HGG5, HG8, HGG11), indicating that genomic data from tumor tissue at recurrence may provide better guidance for therapeutic choices." (PMID 29084603, 2017). "We used the nCounter expression assay (NanoString®) to measure the expression of EGFR, erb-B2 receptor tyrosine kinase 2 (ERBB2), ERBB3, ERBB4, and estrogen receptor 1 (ESR1) genes using mRNA extracted from paraffin-embedded tumor tissues from 203 patients diagnosed with TNBC." (PMID 26907936, 2016). "We therefore evaluated whether EGFR, ASAP1, ERBB2 and ERBB4, which signal downstream after ligation of EGF, and which show aberrant expression in several other invasive cancers, would also predict HBL tumor invasiveness." (PMID 27910913, 2016). "Reduced ERBB4 expression was confirmed by IHC in CHLA-9 control implantation site tumours compared to strong ERBB4 immunostaining in both CHLA-9/ERBB4 implantation site and metastatic tumours." (PMID 23681745, 2013). "We found that ERBB4 kd blocks Tyr-397 phosphorylation, the major autophosphorylation site of FAK, as well as overall FAK activation under cell spreading conditions, an early step in tumour cell migration and invasion." (PMID 23681745, 2013).
tumor (continued). "Nuclear-localised ErbB4 intracellular domain may act as a transcription coactivator whereas the cytoplasmic/mitochondria-localised ErbB4 intracellular domain may act as a BH3-only protein and induce apoptosis in tumour cells." (PMID 21364581, 2011). "The tumor promoting effect of the HCV transgene may be explained both by upregulation of pro-tumorigenic genes as Ubd, Erbb4, Nrg1, Ndrg1, Styk1, and by evasion of host defense response by viral proteins." (PMID 19340302, 2009). "Tumours from bitransgenic mice overexpress the myr-Akt1 and ErbB2 transgenes, but there was dramatically less overexpression and phosphorylation of ErbB3, diminished phosphorylation of ErbB2, decreased level of EGFR protein and undetectable ErbB4 protein." (PMID 18700973, 2008). "Certain target genes (e.g., ERBB4, SEMA4A, GCNT2 and SOX4) play critical roles in shaping two pathways related to the malignant fate of AT2 cells, which are inseparable from tumor differentiation and migration, suggesting that these genes may be novel therapeutic targets for further studies." (PMID 41415280, 2025). "Tumour cells with diminished endocrine signalling can bypass CDK4/6 inhibition through upregulation of the JNK pathway and showed that in cancer cells with high oestrogen signalling, potentiation of CDK4/6 activation can occur through ERBB4 and ERK upregulation and activation." (PMID 35800379, 2022). "In addition, GATA3, ERBB4, RET, NAT, and TFF3 genes are commonly expressed in tumor cells, which may also influence response to treatment." (PMID 36536751, 2022). "The role of ERBB4 as a tumor progression factor is not fully elucidated." (PMID 33503190, 2021). "ERBB4 itself could not induce tumor transformation of mouse colonocytes, while under the condition of colonocytes with mutant Apc and Ras, ERBB4 enhanced the transformed phenotype both in vitro and in vivo." (PMID 32117908, 2020). "To determine whether this decrease in graft mass and volume reflected decreased tumor cell proliferation or survival, we quantified the Ki67 and TUNEL labeling indices in five Erbb4-ablated and five control grafts established from each of the three early-passage cultures." (PMID 31291965, 2019). "Although ERBB4 has been found in normal heart and human umbilical cord endothelium, and has been suggested to play a role in heregulin-induced angiogenesis, it has not previously been identified in tumor endothelium or on pericytes in GBM." (PMID 30044378, 2018). "However, IHC staining showed that cytoplasmic ERBB4 expression only occurred in tumor tissues and not in adjacent normal tissues." (PMID 28042953, 2017). "Given that the H3K27me3-associated genes tend to be transcriptionally silent in normal tissue and hypermethylated in tumours, it can be speculated that ERBB4 methylation has no biological meaning in colorectal carcinogenesis." (PMID 25366420, 2015). "In contrast, transgenic expression of truncated ERBB4 isoforms did not induce neoplasia." (PMID 25516216, 2014). "This suggests that the absence of tumor suppressor activity displayed by these mutants may be a result of ErbB4 mislocalization." (PMID 24791013, 2013). "Indeed, ER+ tumours were scattered in subgroups 1 to 4 that are characterised by the over-expression of a cluster of genes, which includes CCND1, KRT19, IGF1R, LIV1, ESR1, GATA3, TFF1/pS2, ERBB4, PR and IGFBP4." (PMID 17338809, 2007). "Mounting evidence indicates that ErbB4, unlike EGFR or ErbB2, functions as a tumor suppressor in many human malignancies." (PMID 24791013, 2013).
tumor (continued). "One possible mechanism is that in the presence of high ERBB2 levels, ERBB4 with bound NRG4 may form ERBB2:ERBB4 heterodimers, which possess oncogenic activity, rather than ERBB4:ERBB4 homodimers, which function as tumor suppressors." (PMID 37174100, 2023).
cancer (312 papers, 2004 to 2026). A tumor composed of atypical neoplastic, often pleomorphic cells that invade other tissues. "Receptor tyrosine kinase ERBB4 (HER4) is frequently mutated in human cancer, and ERBB4 mutations have been identified in patients relapsing on targeted therapy." (PMID 41437739, 2025). "Together, these results are expected to facilitate clinical interpretation of the most recurrent cancer-associated ERBB4 mutations." (PMID 41437739, 2025). "Here, we addressed the functional consequences of recurrent cancer-associated ERBB4 mutations that are located at regions important for receptor activation and/or are paralogous to known oncogenic hotspot mutations in other ERBB genes." (PMID 41437739, 2025). "ERBB4 is expressed in many human tissues and is mutated in such cancers as colorectal (CRC), non-small cell lung (NSCLC), or breast cancer." (PMID 39340537, 2024). "The association to ERBB4 was certainly intriguing since GRs are predisposed to cancer and ERBB4 is a member of the EGFR family of oncogenes." (PMID 37855863, 2024). "Nuclear signaling mediated by ERBB4 was upregulated in Black samples in four cancer types, an important finding considering that overexpression of the kinase is associated with cancer development." (PMID 37345032, 2023). "The significance of multiple ERBB4 mutations and the eventual frequency of functional ERBB4 mutations in the different cancer sample series thus remain to be elucidated." (PMID 36860695, 2022). "Generally, cancer has been linked to mutations in the ERBB4 gene, which in this study was confirmed as a highly unstable gene." (PMID 36077746, 2022). "Here we addressed the functional significance of 93.5% of all theoretically possible missense and nonsense mutations of a single cancer gene, ERBB4, in an unbiased functional genetics screen." (PMID 36860695, 2022). "The data indicate the presence of rare activating ERBB4 mutations in cancer, with potential to be targeted with clinically approved pan-ERBB inhibitors." (PMID 36860695, 2022). "The Kaplan–Meier survival analysis indicated that the mutation status of ERBB4 was associated with the prognosis of cancer patients receiving ICIs treatment (p = 0.0130)." (PMID 34620079, 2021). "The somatic mutations of the organoids were identified and cancer genes in the most relevant BC genes were also found, including ERBB4, HLA-DRB1, PDE4DIP, PTPN22." (PMID 32774159, 2020). "We used the crystal structures of the EGFR, ErbB2, ErbB3, and ErbB4 kinases that constitute this family to perform rigidity decomposition and then align the positions of the predicted cancer driver mutations with the structural mobility maps." (PMID 31245384, 2019). "The human epidermal growth factor tyrosine kinase receptor (EGFR/ERBB) family, which includes four members: HER1 (EGFR, ErbB1), HER2 (Neu, ErbB2), HER3 (ErbB3), and HER4 (ErbB4) have been associated with many human cancers." (PMID 31470531, 2019). "We found that predicted cancer driver mutations are mapped onto more stable regions in ErbB4, owing to the greater rigidity of this catalytic domain." (PMID 31245384, 2019). "160/18324 (0.87%) of all cancers have putative ERBB4 driver mutations (defined as frequency>5 in cBioPortal or COSMIC databases, or a HotSpot or OncoKB driver annotation in cBioPortal) as per the cBioPortal and GENIE databases." (PMID 29371993, 2017). "In kinome-wide screens for cancer-causing mutations, some of the ErbB4 mutants, including D818N from the HRD catalytic motif and D836Q of the DFG motif revealed a severely suppressed kinase activity." (PMID 25427151, 2014). "Two (0.2%) ERBB4 kinase domain mutations were found, both of which have previously been shown to be functional and promote cancer cell growth in vitro." (PMID 25036186, 2014).